HTT (huntingtin)
Diseases named in the same sentence as HTT in open-access papers (continued):
Sharing a sentence is not in itself a finding about the gene and the disease.
movement disorder (11 papers, 2016 to 2024). Neurological conditions resulting in abnormal voluntary or involuntary movement, which may impact the speed, fluency, quality and ease of movement. "However, features of movement disorder were different to that of N171-82Q Tg mice (expressing a mutant N-terminal fragment of HTT), which displayed loss of coordination, hunched posture, tremors, abnormal gait, and clasping of hindlimbs." (PMID 29946240, 2018). "This suggests that there are specific effects of neuronal mutant huntingtin on specific peripheral tissues, and highlights the importance of studying multiple types of skeletal muscle in models of movement disorders like HD." (PMID 37823007, 2023). "In our study, four unrelated patients presented with a movement disorder, and genetic studies revealed expanded CAG trinucleotide repeats in the HTT gene, which is consistent with the diagnosis of HD." (PMID 35733931, 2022). "Other genes, such as GAK, HTT, TMEM175, FAM193A, and DGKQ, were mainly related to movement disorders (adjusted p-value = 0.0001) and basal ganglia disease (adjusted p-value = 3.73e-05)." (PMID 28118382, 2017).
tumor (10 papers, 2009 to 2025). "Correlative studies have highlighted a decreased cancer incidence in the population with the neurodegenerative disorder Huntington’s disease and both wild-type and mutant huntingtin (Htt) have been implicated in tumor progression." (PMID 33465062, 2021). "We previously identified PFN1 as a huntingtin aggregation inhibitor, and others have implicated it as a tumor-suppressor." (PMID 22479341, 2012). "Because PI3K/Akt and MAPK pathways are often aberrantly activated in tumor cells, and they are reported to be associated with Cdc42 and huntingtin, thus we performed qRT-PCR to determine the mRNA expression of Akt and MAPK14 (encoding p38 MAPK) in Trip10-overexpressed CP70 and IMR-32 cells." (PMID 21299869, 2011). "Present observations help to understand the factors that affect HDFs in the microenvironment of FD exposed keratinocytes and the therapeutic role of HTT as a suppressor of skin aging." (PMID 33925954, 2021). "The expression of ARRB1, FLNA, CALM3 and HTT was found to be localized predominantly in the cytoplasm of the tumor cells." (PMID 28559546, 2017). "Most of the genes affected by polyQ-huntingtin expression (73%) were up-regulated in the tumours expressing polyQ-huntingtin compared to their expression levels in the wild-type tumours." (PMID 23300147, 2013). "Tumours bearing mutant huntingtin have a modified gene expression pattern that reflects enhanced aggressiveness with the overexpression of genes favouring invasion and metastasis." (PMID 23300147, 2013). "In summary, mutant huntingtin expression in primary tumour tissue and in tumour-derived cells affects the levels of known cell adhesion markers and mesenchymal markers." (PMID 23300147, 2013). "Furthermore, when mutant huntingtin is expressed, tumour cells in culture adopt an altered morphology resembling a mesenchymal phenotype." (PMID 23300147, 2013). "Furthermore, Trastuzumab treatment was accompanied by an inhibition of ErbB2 triggered signalling in polyQ-huntingtin-expressing tumour cells." (PMID 23300147, 2013). "We investigated whether huntingtin could interact with dynamin in primary tumours cells and the possible consequence of the abnormal polyQ expansion in mutant huntingtin." (PMID 23300147, 2013). "In agreement with the earlier appearance of the tumours expressing mutant huntingtin as compared to the one expressing wild-type huntingtin, the biological processes of several GO categories related to cell death, apoptosis and proliferation were also affected (p-values smaller than 5 × 10−2)." (PMID 23300147, 2013). "Thus the genetic signature of tumours expressing polyQ-huntingtin may correlate with their earlier appearance as compared to the one of tumours expressing wild-type huntingtin." (PMID 23300147, 2013). "In contrast, for the primary tumor cell line SW480, only 3 genes (HIP1, HSPH1, HTT) showed significant oscillations." (PMID 32295075, 2020). "Compared with MMTV-PyVT mice expressing wild-type huntingtin (MMTV-PyVT/HdhQ7/Q7), tumours appeared earlier in MMTV-PyVT/HdhQ111/Q111 mice." (PMID 23300147, 2013). "Thus lack of Akt3 expression along with high level of endogenous huntingtin in CP70 cells may be the determinant factors of Trip10-induced tumor suppression." (PMID 21299869, 2011).
brain disorder (8 papers, 2018 to 2024). A disease affecting the brain or part of the brain. "HD is a brain disorder caused by the mutations of the huntingtin (Htt) gene." (PMID 34944433, 2021). "HD is a progressive brain disorder that causes uncontrolled movements, emotional problems, and loss of thinking ability (cognition) caused by trinucleotide (CAG) repeat expansion in the huntingtin (HTT) gene, resulting in a toxic huntingtin protein." (PMID 29751665, 2018).
infection (6 papers, 2010 to 2024). The state of being infected such as from the introduction of a foreign agent such as serum, vaccine, antigenic substance or organism. "Lentiviral-mediated infection with the shRNAs led to selective degradation of mutant HTT mRNA and prevented the apparition of neuropathology in HD rat's striatum expressing mutant HTT containing the various SNPs." (PMID 24926995, 2014). "Cells were differentiated, infected with either AAV‐CaM‐peptide + GFP, AAV‐scram‐CaM‐peptide + GFP or AAV‐GFP (MOI = 50), and forty‐eight hours post‐infection cells were assayed for TG‐modified N‐terminal mutant huntingtin." (PMID 19338577, 2010).
psychiatric disorder (6 papers, 2011 to 2025). A disorder characterized by behavioral and/or psychological abnormalities, often accompanied by physical symptoms. "It is triggered by a mutation in the HTT gene that strongly influences functional abilities and usually results in movement, cognitive and psychiatric disorders." (PMID 26667114, 2015). "In summary of these frequency analyses we extend the current literature on the role of huntingtin for psychiatric disease risk that a critical threshold of ~21 CAG repeat counts of the longer allele might play a role for psychiatric risk, yet depending on age." (PMID 39572770, 2025). "Cognitive, motor, and psychiatric disorders are associated with rare, inherited HD diseases characterized by an autosomal mutation responsible for an increase in the number of CAG repeats in the huntingtin (HTT) gene." (PMID 39000116, 2024).
heart disease (4 papers, 2011 to 2022). "Our bioinformatic analysis highlighted a network in which huntingtin protein was found to be at the center of a cluster of mitochondrial proteins, but its precise function in heart disease remains to be elucidated." (PMID 24303125, 2013).
neurodevelopmental disorder (4 papers, 2017 to 2025). A behavioral and cognitive disorder with onset during the developmental period that involves impaired or aberrant development of intellectual, motor, or social functions. "There are reports of seizures in the neurodevelopmental disorder, LOMARS, a syndrome defined by putative HTT loss of function variants." (PMID 37199581, 2023).
metabolic disease (2 papers, 2024 to 2025). A congenital disorder (due to inherited enzyme abnormality) or acquired (due to failure of a metabolically important organ) disorder resulting from an abnormal metabolic process. "In addition, the 4 VUS identified in this study (CFTR: rs1800120, TBC1D24: rs754558646, HTT: rs779780620, and FDX2: rs897162037) were found to coexist with several other P/LP variants or VUS in genes associated with cardiovascular/metabolic diseases or CoQ deficiency." (PMID 38844616, 2024).
HTT also shares sentences with these, for which no sentence is quoted: Parkinson’s (17 papers); dentatorubral-pallidoluysian atrophy (4); fragile X syndrome (4); Kennedy disease (4); Machado-Joseph disease (4); multiple system atrophy (4); myotonic dystrophy (4); neurotoxicity (4); psychiatric disturbances (4); spinal muscular atrophy (4); spinocerebellar ataxia 2 (4); Ataxia (3); autism (3); cardiovascular disease (2); colorectal cancer (2); Creutzfeldt-Jakob disease (2); Dyskinesia (2); familial amyotrophic lateral sclerosis (2); glaucoma (2); multiple sclerosis (2); myotonic dystrophy type 2 (2); Onset (2); ovarian carcinoma (2); primary torsion dystonia (2); spinocerebellar ataxia 7 (2); synucleinopathies (2); transmissible spongiform encephalopathies (2); Apathy (1); asthma (1); atherosclerosis (1).
A further 56 diseases each share a sentence with HTT in 1 paper.